IL17A (interleukin 17A)
Diseases named in the same sentence as IL17A in open-access papers (continued):
Sharing a sentence is not in itself a finding about the gene and the disease.
infection (continued). "The modest rise in IL-17A levels after RS—contrasted with its steady decline following OS—may enhance resistance to postoperative infections, consistent with lower infection rates observed after RS." (PMID 41155334, 2025). "During infection, IL-17A can positively regulate IFN-γ production, although the mechanism is unknown." (PMID 39504049, 2024). "ETBF infection promotes tumorigenesis via IL-17A/CXCL1 inflammatory cytokines." (PMID 39330861, 2024). "The expression levels of interleukin 1 beta (IL-1β), IL-6, IL-8, IL-10, IL-17A, and the interleukin receptor IL-17RA were significantly increased after infection with Yb2 and cYb2ΔsspA and were much greater than those in the brains of control and Yb2ΔsspA-infected ducks at 24 and 48 hpi." (PMID 38594770, 2024). "However, contradictory findings have been reported, indicating the down-regulation of IL-17A expression in the cecum after primary infection with E. tenella." (PMID 39576763, 2024). "We detected a significant upregulation of both Il17a and Il17f in young VI mice (VI vs. V), while only Il17a was found upregulated in young NI mice (NI vs. N), which suggested a more robust Th17 response following vaccination and subsequent infection." (PMID 38932347, 2024). "For instance, it appears that these cytocines as proinflammatory factors should increase during infection; IL‐6 and IL‐17A follow this rule, but IL‐F exhibits decreasing results in the study of the plasma concentration of secreted cytokines in toxoplasma patients." (PMID 38270309, 2024). "However, 5-OP-RU treatment of mice during the chronic phase of infection was effective in reducing the bacterial burden in an IL-17A–dependent manner." (PMID 38716731, 2024). "However, the infection mechanism of IL-17A in the incidence and development of cow bacterial mastitis needs to be further investigated, attracting more and more attention from veterinarians and medical researchers." (PMID 38891619, 2024). "IL-17A mRNA was reduced to almost background levels in VACV-infected TCRδ−/− mice 5d post-infection, a time point that precedes the later infiltration of TCD4+ that may produce IL-17A." (PMID 38543790, 2024). "Lungs infected with the highly virulent strain 04–303 showed an increase of IL-17A immunostained cells in the interstitial, peri-bronchial, and perivascular inflammatory infiltrate during the first and second weeks post-infection, with a peak after 14 days of infection." (PMID 39024223, 2024). "Notably, FcεR1γ-deficient ILC3s showed a significant decrease in the expression of infection-induced immune activation genes, such as Fcgr3, Ccr7, Il22, Il17a and Cd93." (PMID 39013884, 2024). "One was at the level of both bacterial cell-structural alterations (as shown by SEM), and the other was at the level of interaction with host tissues (as demonstrated using an ex vivo biofilm infection model on skin samples, with experiments for production of NO and IL-17A)." (PMID 39770872, 2024). "Because neutrophils are known effectors of the type 17 response and were significantly decreased in anti-IL-17A-treated mice, understanding the impacts of IFNλ specifically on this cell type may explain downstream effects seen during super-infection." (PMID 39178311, 2024). "These were registered on the level of both bacterial cell-structural alterations (demonstrated by scanning electron microscopy) and the interaction with host tissues (ex vivo biofilm infection model on skin samples with tests on nitric oxide and interleukin (IL)-17A production)." (PMID 39770872, 2024). "Reports have shown that IL-17A+ γδ T cells could protect against infection and promote inflammation in the liver." (PMID 37475963, 2023). "However, using a model of infection with the lung-migrating nematode Nippostrongylus brasiliensis (Nb), we recently demonstrated that IL-17A is also necessary to mount a pulmonary type 2 response." (PMID 37783278, 2023).
infection (continued). "In this brief report, we demonstrate that deficiency of IL-17A leads to impaired IL-33 expression and secretion early in infection, independent of IL-17A suppression of IFN-γ." (PMID 37783278, 2023). "The magnitude of the IL-17A response may help determine the fate of infection; high levels of IL-17A promote clearance of S. aureus SSTI17,53." (PMID 36693884, 2023). "IL-17 (a pro-inflammatory cytokine) expression increases in the intestine of chickens in response to infection with CP; IL-17A is important in inflammation and antimicrobial defense against pathogens (extracellular bacteria and fungi) at mucosal surfaces and regulates mucosal immune defenses." (PMID 37107286, 2023). "Inflammation, infection, stress and other factors can induce the increase of IL-17A." (PMID 37978543, 2023). "Anti-TNF-α or anti-IL-17A Ab treatment suppressed the infection-induced upregulation of MMP-8." (PMID 37939119, 2023). "Viruses can utilize IL-17A to modulate the host immune system to support productive infection." (PMID 37631976, 2023). "Although we observed an increase in the frequency of IL-17A+ Teff cells and circulating IL-17A in both males and females, we only observed an upregulation of the cognate IL-17A receptor (Il17ra) in the iWAT of male mice during infection." (PMID 37923768, 2023). "Thus, the IL-23/IL-17A axis plays a critical role in the initial host defense against pathogen (viral and bacterial) infection by stimulating Th17 cells and unconventional T cells." (PMID 37334361, 2023). "In particular, IL-17A activates Th17 immunocytes in response to tissue-resident infection." (PMID 38152404, 2023). "In contrast, although naive l17af−/− female mice have a higher bodyweight than their C57BL/6 counterparts, they experience similar levels of wasting as C57BL/6 females upon infection, supporting our hypothesis that the effects of IL-17A/F are sex-dependent." (PMID 37923768, 2023). "This may indicate that of all the cells within the iWAT stroma, preadipocytes increase their responsiveness to IL-17A during infection." (PMID 37923768, 2023). "This could suggest that the iWAT becomes more responsive to IL-17A signalling in males than females during infection." (PMID 37923768, 2023). "In fact, LTi cells produce IL-22, IL-17A, and IL-17F as a result of RORγt expression and are involved in the creation of secondary lymphoid organs during embryogenesis and maturity, as well as in their restoration after infection." (PMID 37047071, 2023). "It was recently demonstrated that IL-17A and IL-17F are drivers of adipocyte lipid usage in adipocytes during infection and, moreover, promote infection-induced cachexia, suggesting that it may drive lipid usage in other cell types, including hepatocytes." (PMID 37371074, 2023). "We also detected that colonic IL-17A contents were elevated after CR infection." (PMID 37111225, 2023). "In addition, the number of IL-17A-producing γδ T cells increased after infection, and these cells were the major IL-17A producers in our model." (PMID 37939119, 2023). "In several studies and models, the impairment of IL-17A and IL-17F has been shown to facilitate infection by different pathogens such as Klebsiella pneumoniae, Francisella tularensis, Pseudomonas aeruginosa, Citrobacter rodentium, Candida albicans, or Staphylococcus aureus." (PMID 37373452, 2023). "However, early IL-17A production has also been described in mucosal CD3+CD4+ T cells after infection of naïve piglets with ETEC expressing F4 fimbriae." (PMID 37809062, 2023). "During an infection or injury, the protective role of IL‐17A changes to a damaging role." (PMID 37249293, 2023). "Furthermore, there was a significant expansion of IL-17A-producing Teff cells, consistent with the transcriptional responses of the iWAT to infection." (PMID 37923768, 2023). "Likewise, on day 104 post-infection cerebral PD-1 and IL-17A showed increased expressions in diabetic animals." (PMID 37719029, 2023).
infection (continued). "Along these lines, hla expression during S. aureus SSTI may limit IL-17A secretion, and infection with Δhla promotes the rapid expansion of Th1 and Th17 cells." (PMID 36693884, 2023). "We next proceeded to resolve the intrinsic heterogeneity of the T cell subset associated with the iWAT, as we wanted to understand precisely which T cells were expressing Il17a and whether these cells expanded during infection, as observed at later timepoints." (PMID 37923768, 2023). "Infections were carried out in wild-type mice (WT) and KO Il17a−/− mice with the H99 strain." (PMID 35208830, 2022). "Quantitative flowcytometric analysis also revealed that after high-dose Mtb infection, the amount of CD11b+ Gr-1+ cells in the lungs of IL-17A−/− mice was approximately five times higher than in the lungs of the corresponding wildtype mice on Day 28 post-infection." (PMID 36139450, 2022). "Indeed, transcriptome analyses revealed increased expression of proinflammatory IL17A, IL17F, and RORC (which encodes the IL-17 transcription factor RORγt38) genes in rAAV-IL-27p28-treated mice early during infection." (PMID 36028492, 2022). "Remarkably, in A, an elevated IL-17A concentration in BAL could be detected after challenge infection." (PMID 36569943, 2022). "In addition to IFN-γ and TNF, the pro-inflammatory cytokine IL-17A also appears to contribute to protective immune responses against infection with Mtb." (PMID 36139450, 2022). "Interestingly, we recently reported that IL-17A transcripts were higher at the early stage (2–4 days post-infection) of SARS-CoV-2 infection in hamsters." (PMID 36298628, 2022). "In contrast, determination of CFUs in the lungs revealed that on Day 143 after infection with an elevated dose of Mtb H37rv, IL-17A/F−/− mice appeared to exhibit a significantly lower bacterial burden when compared with both the IL-17A−/− mice and the wildtype controls." (PMID 36139450, 2022). "APECED patients feature selective infection susceptibility to CMC with a frequency of ~80-90%, associated with serum autoantibodies against IL-17F (frequency, ~20-85% depending on the cohort), IL-17A (frequency, ~35%), and IL-22 (frequency, ~70-90% depending on the cohort)." (PMID 34964702, 2022). "Our data indicate that IL-17A is involved in the secretion of cytokines and chemokines with an effect on the recruitment and activation of neutrophils and their migration to the site of infection." (PMID 35805137, 2022). "The authors could show that when intestinal epithelial cells were treated with IL-17A or IL-17F, intracellular survival of C. jejuni was significantly decreased, emphasizing the importance of these cytokines in human infection." (PMID 36248804, 2022). "Numerous mouse studies showed that infection with mucoid and non-mucoid P. aeruginosa strains is associated with increased pulmonary expression of IL-17A." (PMID 35883573, 2022). "On the basis of these findings, we speculated that, in contrast to the minor impact of IL-17A during a low-dose infection with Mtb H37rv, the cytokine may exert a larger influence in response to infection with higher doses of the laboratory-adapted Mtb strain." (PMID 36139450, 2022). "A lower IL-17A response in DC may have contributed to the increased colonization observed at 12-days post-infection." (PMID 36704785, 2022). "However, some studies have found that IL-17A in the lungs is markedly elevated in mice after infection with this pathogen." (PMID 36558881, 2022). "IL-17A and IL-22 are proinflammatory Th17 cell cytokines that synergize to promote neutrophil recruitment early after infection, and increase neutrophil bactericidal activity via enhanced production of defensins and calcium binding proteins, resulting in pathogen clearance." (PMID 36060742, 2022). "In addition, treatment of WNV-infected mice with recombinant IL-17A up to day 6 after infection reduces the viral replication and increases survival suggesting a protective effect of this cytokine in WNV infection." (PMID 36366333, 2022).
infection (continued). "In DC, Il17a mRNA was significantly induced by infection (25.2-fold, p = 5.58E-03)." (PMID 36704785, 2022). "However, in an experimental infection of humans with Ascaris suum, the level of IL-17A was decreased while IL-4 and TGF-beta were increased." (PMID 35976976, 2022). "The early phase (3 h post-infection [hpi]) is characterized by the upregulation of several genes for proinflammatory cytokines related to the mucosal immune response (il17a/f1 and il20) along with genes for antiviral cytokines (il12β) and antiviral factors (ifna and ifnc)." (PMID 35432241, 2022). "However, neutralization of IL-17A during early infection significantly reduced bacterial burden, fibrotic lung damage, and mortality in chronically infected mice." (PMID 35363832, 2022). "IL-17A and IL-17F protects against bacterial and fungal infections by recruiting neutrophils and inducing antimicrobial proteins at the site of infection, though IL-17C and IL-17E may vary in function in antifungal/antibacterial immunity." (PMID 35805960, 2022). "Moreover, here, we demonstrated that, similar to what was observed in the context of hypervirulent Mtb, IL-17A contributes to protection after infection with an elevated dose of Mtb H37rv (probably mimicking higher virulence)." (PMID 36139450, 2022). "While these discrepancies might also relate to the magnitude of NO, it is important to mention that we were unable to detect the exact T cell population that was responsible for IL-17A production in LgyLRV1+ infection." (PMID 36034693, 2022). "Thus, the exact relation between LRV1-triggred iNOS and IL-17A production in LgyLRV1+ infection of Ifn-γ-/- mice is still unclear and requires further investigation." (PMID 36034693, 2022). "Mouse models of RSV infection showed that administration of an anti-IL-33-receptor antibody that blocks the IL-33 cascade can reduce both the Th2 and Th17 environment (especially IL-13 and IL-17A) and the eosinophil recruitment induced by IL-33 after infection." (PMID 35327516, 2022). "Interestingly, the presence of neutrophils isolated during primary infection also enhanced by two fold the capacity of CD4+ T-cells to produce IL-17A (p < 0.001)." (PMID 35185880, 2022). "The risk of infection may also increase if levels of calprotectin, chemokine CXCL1, and cytokines Il-17A, IL-17F, Il-6, and IL-1β are also reduced." (PMID 35979535, 2022). "IL-17A was increased in the lungs at 1–2 weeks of infection and reduced at 3 weeks postinfection." (PMID 35363832, 2022). "In addition, the Th17 signature cytokine IL-17A and its master transcription factor, RORc, were also found to be elevated in early phase of infection." (PMID 35014610, 2022). "However, at 39 weeks post-infection, anti-IL-17A mAb treatment significantly enhanced lung IL-4 and IL-22 levels compared to isotype-matched control Ab treatment in the lungs of M. intracellulare-infected mice." (PMID 35363832, 2022). "Similarly, Lm-elicited memory Vγ4 T cells are the primary source of IL-17A one day after Lm challenge infection of previously immunized young adult mice, which promotes the control and clearance of Lm." (PMID 35501808, 2022). "It is worthy of consideration the protective role of IL-17A in host defense against infection when blocking IL-17 pathway, as it could bring detrimental harm." (PMID 35603223, 2022). "Interestingly, the infection of chickens with C. jejuni significantly upregulated (P < 0.05) the expression of the IL-10 (2.7 fold), IL-17A (2.9 fold), IL-1β (1.9 fold), IFN-γ (1.5 fold), and CXCLI1 (1.8 fold) genes compared to NC group." (PMID 36135600, 2022). "Furthermore, the production of the cytokines IL-17A and IL-4, originating mainly from innate immune cells, seems to be important for controlling the larval lung burden at the beginning of the infection." (PMID 35844540, 2022).
infection (continued). "All mice neutralized of IFNγ fatally succumbed to WT infection within 20 days, while a ~35% survival rate was observed for mice with abrogated IL-17A signaling either through direct cytokine neutralization or IL-17-directed effector cell depletion (i.e., neutrophils)." (PMID 36229573, 2022). "Markers associated with a protective immune response, such as IL-17A and mannose binding lectin 2 were still significantly upregulated following infection in the antibiotic-treated mice, despite the lack of protection." (PMID 34011991, 2021). "IL-17A may be relevant for infection clearance, but has also been suggested to contribute to pathogenesis due to the stimulatory effects of IL-17A on bone destruction and tissue damage." (PMID 34240122, 2021). "In theory, IL-17A helps clear bacteria by recruiting neutrophils to the infection site." (PMID 33879639, 2021). "The innate response to HRV16 infection was comparable in IL-17A-treated and control cells." (PMID 34140575, 2021). "However, we propose that the same molecular responses that are beneficial in the early stages of infection become dysregulated by the unresolved focus of infection in active TB disease, ultimately driving IL-17A/F-mediated immunopathology." (PMID 33952677, 2021). "Since IL-33 treatment does not impair the immune response in the late phase of CR infection, it is likely that IL-17A has the power to counterbalance the early pathogenic potential of IL-33 within the gut." (PMID 33654214, 2021). "The protein level of IL17A was up-regulated at 2 folds (p < 0.0001) at 48 h after GS2018 infection." (PMID 34872498, 2021). "Similarly, also vaccinated IL-17A−/− mice showed enhanced frequencies of IFN-γ−TNF+IL-2+ multifunctional CD4 T cells until week 6 post-infection." (PMID 34351501, 2021). "SARS-CoV-2 virus evokes an exacerbated response of the host’s immune system but differs from that observed in the H1N1pdm09 infection since the IL-8/IL-17A tissue expression, and lung neutrophilic recruitment may be decreased." (PMID 33868301, 2021). "Inflammatory cells infiltrate the sites of infection at an early stage of the infection with SARS-CoV2 and cause a stormy release of pro-inflammatory cytokines like IL-6, IL-17A, TNFα, IFNγ, IL-1α/β, and chemokines like CC-chemokine ligand 2 (CCL2) as well as CXC-chemokine ligand 10 (CXCL10)." (PMID 33643316, 2021). "Indeed, we observed that the re-establishment of IL-17A levels counteracts the strong systemic microbial dissemination elicited by IL-33 treatment during CR infection." (PMID 33654214, 2021). "Finally, the role of IL-17A in infection clearance was addressed, with the use of IL-17A KO animals." (PMID 34240122, 2021). "In the later course of infection, IL-17A (which shares the receptor IL-17RA with IL-17C) released from immune cells such as γδ T cell may compensate the loss of IL-17C-signaling in S. aureus-infected wounds." (PMID 34576717, 2021). "Interestingly, the proviral effects of IL-17A signaling on MHV68 infection, including germinal center response, were selective for the intranasal, but not intraperitoneal, route of inoculation." (PMID 33824206, 2021). "Additionally, the exogenous administration of IL-17A significantly reduced the bacterial load after infection." (PMID 33879639, 2021). "Moreover, pdmH1N1 infection induced a significant increase of IL-17A production in lung-infiltrating γδ T cells." (PMID 33772013, 2021). "The authors concluded that IL-17A produced mainly by Th17 cells during secondary infections may play an important role during the “cytokine storm” and, consequently, contributes to dengue immunopathogenesis." (PMID 34064728, 2021). "Immune cell numbers and IL-17A production were also examined in the spleen 24 h post-infection." (PMID 34358191, 2021). "Taken together, we hypothesize that exaggerated IL-17A/F recall responses in active TB are the consequence of chronic multibacillary infection that mediates increased pathology in established TB disease." (PMID 33952677, 2021).